ERBB2 (erb-b2 receptor tyrosine kinase 2)
Diseases named in the same sentence as ERBB2 in open-access papers (continued):
Sharing a sentence is not in itself a finding about the gene and the disease.
breast cancer (continued). "For example, the expression of ERBB2 correlates adversely with outcome in breast cancer It is now possible to address this issue immediately by examining the TCGA data initially and then confirming the results in a separate dataset." (PMID 33488950, 2020). "For example, the association between age and tumor grade, Ki-67 markers, apoptosis index, EGFR expression and erbB-2 expression has been reported in breast cancer." (PMID 32819307, 2020). "In particular, YWHAZ overexpression, ErbB2 overexpression, and positive lymph node status were seen to be independent prognostic factors in breast cancer." (PMID 32127952, 2020). "Trastuzumab deruxtecan was approved by the FDA in 2019, for treatment of ErbB2+ advanced breast cancer patients who have received prior ErbB2-directed therapies in the metastatic setting." (PMID 33081383, 2020). "Patients with breast cancers overexpressing HER2 or with amplification of ERBB2, which include 20–25% patients, clinically benefit of regimens combining chemotherapy and HER2-targeted agents." (PMID 33167363, 2020). "Further development of this ADC has now been discontinued owing to disappointing results in a phase II clinical trial for advanced ErbB2-positive breast cancer patients." (PMID 33081383, 2020). "The HER2/neu gene status (ErbB2) is one of the mainindicators used to identify breast cancer subtypes, predict diseaseprogression, and choose treatment options for patients." (PMID 32742732, 2020). "Brk is co-amplified and co-expressed with the receptor tyrosine kinase ErbB2/HER2 in human breast cancers and cooperates with ErbB2 to stimulate downstream signaling." (PMID 32545875, 2020). "One of the indicated proteins is PERP that, according to our previous studies, represents an important mediator of ErbB2 signaling: we observed in the past that ErbB2-driven downregulation of PERP is critical for 3D growth of breast cancer cells." (PMID 33023655, 2020). "While a clinical trial of everolimus in ERBB2 + breast cancer demonstrated an improvement in progression free survival (PFS) when added to the combination of vinorelbine and trastuzumab but the trial failed because of toxicity." (PMID 31988290, 2020). "EGFR is a therapeutic target in basal-like breast cancer, ErbB-2 is a target in the ErbB-2 overexpressing breast cancers, and ER-α is a target to hormone therapy in luminal breast cancers." (PMID 32466213, 2020). "TM4SF1, one of the upregulated signature genes, is a known multiorgan metastasis-promoting gene, and knockdown of TM4SF1 significantly reduces brain metastasis in mouse mammary tumor cells transformed with rat erb-b2 receptor tyrosine kinase 2 (Erbb2)." (PMID 32640677, 2020). "For example, breast cancer patient stratification strategies based on ER/PR and ERBB2 status have proven to be very informative, both in terms of prognosis and response to treatment." (PMID 32907621, 2020). "It is important to note that PI3K is also activated in breast cancers through mechanisms different from PI3KCA mutations, such as ERBB2 amplifications and PTEN loss of expression." (PMID 32210163, 2020). "Of 320 124 women diagnosed with breast cancer from 2010 to 2016, 232 558 (72.6%) had luminal A, 35 869 (11.2%) had luminal B, 15 472 (4.8%) had ERBB2-enriched, and 36 225 (11.3%) had triple-negative breast cancer subtypes." (PMID 32804214, 2020). "Taking advantage of the successful development of the USP2 inhibitor ML364, we investigated the influence of pharmacological USP2 inhibition on ErbB2 expression in breast cancer cells." (PMID 32327714, 2020). "In particular, around 20% of breast cancers (BrCa) display overexpression of ERBB2 (ERBB2-BrCa), leading to a more aggressive clinical course and a worst outcome." (PMID 33037285, 2020). "Amplifications of the locus surrounding ERBB2 is specific for breast cancer and is rarely seen in other cancer types besides a sub-set of gastric adenocarcinomas." (PMID 32987805, 2020).
breast cancer (continued). "The role of PAX2 regulating the transcription of ERBB2/HER2 in breast cancer was previously reported in ER+ cells treated with Tam." (PMID 32843722, 2020). "In the following steps, the breast cancer cells were incubated with a specific biotin-conjugated anti-ErbB2-Affibody, fixated with paraformaldehyde to prevent artificial clustering of labels, and marked with fluorescent, streptavidin-conjugated QDs." (PMID 32714928, 2020). "We illustrate the potential microscaled proteogenomics in a proof-of-principle breast cancer clinical study designed to detect the immediate effects of inhibiting the ERBB2 pathway." (PMID 31988290, 2020). "In vitro studies have shown that ErbB2/ErbB3 heterodimers act as an oncogenic unit to induce breast cancer cell proliferation via PI3K/AKT signaling." (PMID 32366937, 2020). "The human epidermal growth factor 2 (HER2, also called ErbB2) protein is overexpressed in 15–30% of breast cancers and prognoses an aggressive tumor type, resistance to chemotherapy, and an increased mortality rate." (PMID 31991749, 2020). "Human epidermal growth factor receptor 2 (HER2, also known as ERBB2) amplification or overexpression is detected in 20–30% of patients with breast cancer and is associated with a poor prognosis." (PMID 33145402, 2020). "We previously demonstrated that PRMT5 inhibition by DS-437 enhances anti-tumor effects of anti-erbB2/neu monoclonal antibody targeted therapy in a drug-resistant syngeneic murine breast cancer model by inhibiting Treg function and induction of tumor immunity." (PMID 32328070, 2020). "In breast cancer, overexpression of hyaluronan synthase 2 increases ErbB2-dependent signaling leading to disease progression, while its suppression leads to an inhibition of tumorigenesis and progression in breast cancer." (PMID 32961706, 2020). "The breast cancers arising in the ErbB2 transgenic also strongly resembled breast cancers arising from ErbB2-iPSC clones injected into the mammary fat pad." (PMID 33196707, 2020). "For instance, epidermal growth factor receptor 2 (ErbB2)-antibody was conjugated to mesoporous ZnO nanofibers for breast cancer diagnosis." (PMID 32695956, 2020). "ErbB2-iPSC clones also gave rise to mammary carcinomas that exhibited dual GFP autofluorescence and ErbB2 membrane red immunofluorescence." (PMID 33196707, 2020). "ErBb2 is located on chromosome 17q21 and was identified in the 1980s due to its overexpression in a human mammary carcinoma." (PMID 33245725, 2020). "To assess the effectiveness of our deconvolution, we first examined the three receptor genes associated with molecular subtypes of breast cancer: the oestrogen receptor (ESR1), progesterone receptor (PGR), and human epidermal growth factor receptor 2 (ERBB2)." (PMID 31308365, 2019). "In agreement with us, both AKT1 and ERBB2 have already been found to be highly expressed in ER+ recurrent breast cancer as possible genes involved in the mechanism of resistance to Tamoxifen." (PMID 31781306, 2019). "ErbB2 is frequently upregulated by its gene amplification in many types of cancers, including breast cancer, and plays a role as an oncogenic protein, which induces tumourigenesis, invasion, and metastasis." (PMID 31831814, 2019). "The synergistic effects of lovastatin with the ErbB2 inhibitor lapatinib were evaluated using an ErbB2-positive breast cancer xenograft mouse model." (PMID 30786890, 2019). "ERBB2 plays a critical role in the pathogenesis of breast cancer and results amplified and/or overexpressed in 20–30% of human breast cancers correlating with poor prognosis." (PMID 30611309, 2019). "To this aim, we used both TNBC MDA-MB-231 cells, and ErbB2-positive breast cancer SK-BR-3 and JIMT-1 cell lines expressing satisfactory levels of PD-L1 on the cell membrane." (PMID 31511565, 2019).
breast cancer (continued). "To directly address the requirement for PRC2/Ezh2 in ErbB2-driven breast cancer progression, we performed a series of experiments where Ezh2 was ablated or down-regulated in ErbB2+ breast cancer models." (PMID 31263101, 2019). "To determine the generality of the effects of modulating NO level, we applied L-arginine or L-NAME to ERBB2-positive (amplified) SKBR3 breast cancer cells." (PMID 31040372, 2019). "In breast cancer, the analysis of single CTC with a diagnostic intention identified preexisting cells resistant to ERBB2-targeted therapies." (PMID 30959764, 2019). "Mammary tumor development in response to a carcinogen or an MMTVc-neu (ErbB2/Her2) transgene was retarded in IkkαS176A/S180A knock-in mouse." (PMID 31792060, 2019). "For example, miR-205-5p directly targeted ERBB2 and p63, leading to resistance to standard therapy for Her2-positive breast cancer." (PMID 31547870, 2019). "Specifically, in ErbB2-positive breast cancer, p130Cas overexpression correlates with poor prognosis and increase metastatization." (PMID 30816273, 2019). "The human epidermal growth factor receptor 2 (HER2 or ERBB2) represents a predictive biomarker integral to the current therapy of breast cancer and gastric cancer showing indisputable clinical success." (PMID 31805897, 2019). "HER2 ChIP-exo was examined in another breast cancer cell line with an amplified ErbB2 locus, the BT474 cells." (PMID 31747426, 2019). "In ErbB2-positive breast cancer lovastatin, a cholesterol-lowering drug sensitized cancer cells to lapatinib and neratinib." (PMID 31878945, 2019). "The patient cohort encompassed all 3 major molecular subtypes of breast cancer (luminal, ERBB2 positive, and triple negative) and both lobular and ductal carcinomas." (PMID 30736836, 2019). "Overall, this study identifies p130Cas/ErbB2 complex as a potential breast cancer target revealing new therapeutic perspectives for protein-protein interaction (PPI)." (PMID 30816273, 2019). "An estimated 15–20% of breast cancers overexpress human epidermal growth factor receptor 2 (HER2/ERBB2/neu)." (PMID 31141894, 2019). "In this study we have profiled HER2 binding to the chromatin in two breast cancer cell lines with an amplified ErbB2 locus." (PMID 31747426, 2019). "Their experimental validation was performed in vitro and in ErbB2-positive breast cancer cellular models." (PMID 30816273, 2019). "For breast cancer, HER2-enriched specific amplification of ERBB2, basal-specific amplification of CCNE1, and luminal B specific amplification of CCND1 were remarkably salient in both TCGA and METABRIC data." (PMID 30885118, 2019). "For example, ErbB2 inhibits PP1-dependent dephosphorylation of AKT in breast cancer cells whereas ErbB inhibitor and Hsp90 inhibitor promote such an event." (PMID 31092266, 2019). "The aim of this study was to investigate the role of STARD10 and ERBB2 cross-talk in breast cancer as consequence of ethanol administration and elucidate the molecular mechanisms." (PMID 30611309, 2019). "cd-CAP also captured subnetworks relevant to the EGFR/ERBB2 signaling pathways, which have distinct expression patterns in specific subtypes of breast cancer." (PMID 30978274, 2019). "In breast cancer, the NF-κB pathway has been shown to be activated downstream of ErbB2, and ErbB2-induced signaling pathways include MAPK and PI3K/AKT." (PMID 31816863, 2019). "Although feline mammary tumors (FMTs) are good models in comparative oncology, scarce data is available regarding the ERBB2 and TOP2α status." (PMID 31301170, 2019). "Antibody-mediated inhibition of this ERBB2/ERBB3/PI3K axis has been a cornerstone of treatment for ERBB2-amplified breast cancer patients for two decades." (PMID 30898150, 2019).
breast cancer (continued). "P120 catenin (p120), a Src substrate that can indirectly activate Rac1 and Cdc42, acts as an obligate intermediate between ErbB2 and Rac1/Cdc42 to modulate the metastatic potential of breast cancer cells." (PMID 30754684, 2019). "We previously showed that SNDX-275, a class I-selective HDACi, induced apoptosis in ErbB2-overexpressing breast cancer cells via down-regulation of both ErbB2 and ErbB3." (PMID 30961642, 2019). "Proteomic analysis of p140Cap interactome in the ERBB2 breast cancer model uncovered the 373 interacting proteins described here." (PMID 31681758, 2019). "Clinically, patients with ERBB2+ breast cancer treated with two approved therapies targeting ERRB2, Herceptin and lapatinib, tend to experience relapses or malignant outcomes, indicating that improvements in anti-cancer treatment are urgently required." (PMID 31083325, 2019). "With the advent of gene expression profiling over the last 15 years, breast cancers have been classified into luminal A, luminal B, human epidermal growth factor receptor 2 (HER2 or ERBB2)-enriched, basal-like, and claudin-low categories." (PMID 31293831, 2019). "For tumor-specific suicide gene activation, the intratumoral injection of vectors with tumor-specific genes, such as erbB-2, which is a promoter in breast cancer, is used." (PMID 31324753, 2019). "Factor 12 also predicts insensitivity to TOP1-poisons and includes the canonical oncogenes such as ERBB2, TGFB3, ESR1 (AR), and FGFR4 that are strongly associated with breast cancer." (PMID 31695042, 2019). "Interaction of YY1 with AP-2 transcription factor induces ERBB2 promoter activity in breast cancer cells." (PMID 31824839, 2019). "Here, we apply an integrative approach involving multiple pre-clinical models and analysis of clinical samples to delineate a pathway mediating the overexpression of key PRC2 subunits in ERBB2+ breast cancer." (PMID 31263101, 2019). "For example, MDM4 and EGFR were enriched in glioblastoma, MYC and ERBB2 were enriched in breast cancer whereas MDM2 was enriched in both." (PMID 30674876, 2019). "Our findings in this study demonstrated that CLCN3 is a potential direct target of miR-205-5p and regulates 3D spheroid proliferation in ErbB2-overexpressing breast epithelial cells and breast cancer cells." (PMID 31608175, 2019). "This is consistent with the pivotal role of the mTORC1/4E-BP axis in regulating EZH2 expression in ERBB2+ breast cancer." (PMID 31263101, 2019). "Treatment of ErbB2-driven breast cancer cells with the biguanide phenformin, which directly inhibits OXPHOS regardless of the presence of c-Src, activated AMPK and inhibited mTORC1, markedly reducing Ezh2 and Suz12 protein expression." (PMID 31263101, 2019). "The different ERBB2 amplification rates among the four groups inspired us to concentrate on the HER2 expression levels of HER2-positive breast cancers according to ER and PR status." (PMID 31410192, 2019). "Future studies will aim to identify and characterize analogous mechanisms mediating metabolic control by c-Src in ErbB2+ breast cancer cells." (PMID 31263101, 2019). "Triple negative (TN) breast cancer is a particular type of breast cancer, which lacks the expression of oestrogen receptor (ER), progesterone receptor (PgR), and ERBB2." (PMID 31341911, 2019). "In ErbB-2 transformed MDA-MB-231 breast cancer cells nuclear TβR1 interacts with hnRNPA1, which serves as a cofactor for the association with purine-rich RNA sequences." (PMID 31416165, 2019). "Considering that lapatinib is more widely administered than neratinib in the clinical treatment of ErbB2-positive breast cancer, we treated the xenograft-bearing mice with lapatinib or the combination of lapatinib and lovastatin." (PMID 30786890, 2019). "Similar to what has been described for ErbB2-positive breast cancer and lung tumour cells, we propose that invading glioblastoma stem cells use collective migration to overcome anoikis." (PMID 31601895, 2019).
breast cancer (continued). "In the subgroup of ERBB2-amplified breast cancers, a high p140Cap status predicts a significantly lower probability of developing a distant event and a clear difference in survival." (PMID 31681758, 2019). "Considering the essential roles of cholesterol in regulating cell membrane rigidity and fluidity, we examined the cholesterol content in cell membranes from these three ErbB2-positive breast cancer cell lines." (PMID 30786890, 2019). "Since our data indicated that CLCN3 is one of the potential targets of miR-205-5p, we investigated the possible biological function of CLCN3 in ErbB2-overexpressing breast epithelial cells and breast cancer cells." (PMID 31608175, 2019). "The cholesterol-lowering medications can hence be exploited for potential combinatorial therapies with ErbB2 kinase inhibitors in the clinical treatment of ErbB2-positive breast cancer." (PMID 30786890, 2019). "The family members of AP-2 regulate the cell growth and differentiation of tissues of ectodermal origin and involved in the regulation c-erbB-2 (HER2) in breast cancer." (PMID 31191821, 2019). "Meanwhile, triple-negative breast cancer (TNBC) lacking the expression of estrogen and progesterone receptors and ERBB2 is a heterogeneous tumor that encompasses several molecular subtypes of breast cancer." (PMID 31069590, 2019). "The overexpression of human epidermal growth factor receptor 2 (ERBB2 or HER2) protein in immunohistochemistry (IHC) stained slides is an important cell membrane biomarker used for breast cancer diagnosis." (PMID 34460463, 2019). "Lovastatin also synergized with lapatinib to strongly suppress the in vivo growth of ErbB2-positive breast cancer xenografts." (PMID 30786890, 2019). "The prognosis for patients diagnosed with ERBB2-amplified (ERBB2+) breast cancer has improved since the introduction of monoclonal antibody therapy in both the adjuvant and metastatic setting." (PMID 30898150, 2019). "The incidence of p95-ErbB2- or ErbB2ΔEx16-upregulated breast cancers is 30% and 90%, respectively, of the total ErbB2-upregulated breast cancers." (PMID 31831814, 2019). "Conversely, in ER and erbB2-positive breast cancer cells, MFG-E8 exhibits tumor suppressive functions and is not regulated by p63." (PMID 31159154, 2019). "Taking Lapatinib as an example, this drug is a dual inhibitor of EGFR and ERBB2 (or HER2), and was initially approved for treating breast cancer with over-expression of HER2." (PMID 30704449, 2019). "Among them, the overexpression of human epidermal growth factor receptor 2 (HER2, also called ErbB2) occurs in roughly 15-20% of breast cancers and is associated with aggressive proliferation and poor prognosis." (PMID 31015833, 2019). "Approximately 15–20% of breast cancers overexpress the receptor tyrosine kinase (RTK) ErbB2/HER2, typically due to ERBB2 gene amplification, which leads to aggressive disease with poor prognosis." (PMID 31263101, 2019). "Here, in contrast, we show that Ezh2 is required for tumor progression beyond an early hyperplastic stage in models of ErbB2-positive breast cancer and for proliferation and tumor growth in established ErbB2+ breast cancers." (PMID 31263101, 2019). "Relative and absolute quantification enabled us to distinguish different expression levels of the ERBB2 gene in re-amplified WTA products of single breast cancer cells with a comparable level of confidence as in the original WTA samples." (PMID 31430289, 2019). "We used a second, independent TMA series containing 131 patient samples of ERBB2+ breast cancer to confirm these correlations specifically within this subtype." (PMID 31263101, 2019). "Basal-like breast cancers can arise from LCs with the oncogenic activation of ERBB2 signaling or the expression of the polyomavirus middle T (PyMT) antigen." (PMID 31013830, 2019). "For this purpose, we used T47D breast cancer cells, which expressed both nectin-4 and ErbB2 at much lower levels than SUM190-PT cells." (PMID 31831814, 2019).